RN7SKP244 (RN7SK pseudogene 244)
Gene: Miscellaneous RNA gene on chromosome 4 (88,583,666 to 88,583,972, reverse strand). Ensembl gene ENSG00000252322.
Homologues: Orthologues: chimpanzee 7SK (93% identical), mouse Gm55016 (44% identical). Paralogues in human: RN7SKP246 (58% identical), RN7SKP174 (58% identical), RN7SKP291 (58% identical), RN7SKP269 (57% identical), RN7SKP78 (57% identical), 7SK (56% identical), RN7SKP50 (56% identical), RN7SKP151 (56% identical), RN7SKP284 (56% identical), RN7SKP48 (56% identical), RN7SKP74 (56% identical), RN7SKP189 (56% identical), and 284 more.